CDH1 (cadherin 1)
Diseases named in the same sentence as CDH1 in open-access papers (continued):
Sharing a sentence is not in itself a finding about the gene and the disease.
cancer (continued). "ZEB1 helps epigenetic silencing of CDH1 by bringing several enzymes to the E-cadherin promoter for epigenetic induction or by inhibiting the expression of stemness-repressing miRNAs to cause a dynamic transition of non-cancerous stem cells into cancer stem cells (CSCs) and vice versa." (PMID 34201896, 2021). "The epithelial phenotype of cancer cells is governed by claudin-1 (CLDN1), claudin-7 (CLDN7), and E-cadherin (CDH1) genes, while the mesenchymal phenotype is regulated by ZEB1, SNAI1, SNAI2, and Vimentin (VIM) genes." (PMID 33670804, 2021). "Both EPCs and CSCs expressed epithelial lineage markers EPCAM and CDH1/E‐CADHERIN at higher levels than did other cell types, suggesting their potential linkage of the cancer EPC types." (PMID 33898197, 2021). "Hnf4a expression resulted in a decreased expression of cancer-promoting factors LSD1, SETD1A, PRMT1, FOXM1, FAK, and SNAI1, and also an increased expression of CDH1." (PMID 34595169, 2021). "Collectively speaking, the increased levels of LLGL2, EGFR and decreased level in CDH1, recorded in the current study, promote EMT and cancer cell migration in BC." (PMID 33073304, 2021). "NSP3 largely resembles low aggressive luminal cancers, with high levels of KRT20, CDH1, and UPKSs, and affectation of the glycolytic pathway." (PMID 34771699, 2021). "The genes selected included epithelial (KRT5, CDH1, EpCAM), mensenchymal (VIM, SNAI1, TWIST), stem (ALDH1A1, PROM1), breast specific (ESR1, PALB2) and other genes related to cell cycle or other cancer pathways (CCND1, CTNNB1, Ki67, etc.)." (PMID 34071445, 2021). "Since it was characterized as a repressor of E-Cadherin gene (CDH1) expression and an inducer of epithelial-mesenchymal transition (EMT) 1, 2, the transcriptional factor Snail1 has attracted the attention from many cancer cell biologists." (PMID 34335957, 2021). "According to previous research reports, among the four significantly regulated downstream genes found in this experiment, CDH1 was considered to be an anti-oncogene, and ETS1, RAF1 and EIF4E play roles in promoting cancer." (PMID 34671562, 2021). "E47, known as a transcriptional repressor, can bind to the E-box elements within the promoter region of CDH1, inhibiting CDH1 transcription and driving the epithelial to mesenchymal transition (EMT) in various cancers." (PMID 34462424, 2021). "Expression of LINC00518 was evaluated, together with CDH1 and VEGFA, two known targets of KDM1A in other cancer models." (PMID 33371395, 2020). "The fluorescent cancer cells were isolated by FACS, lysed, and analyzed for their E-cadherin and cadherin-11 protein and mRNA levels." (PMID 32752204, 2020). "Among them, CDH1, ETNK2, ADARB2, and RAB40C are found to be aberrantly methylated in different cancers." (PMID 32961999, 2020). "HOX genes are in the spotlight of cancer research due to their effects on key molecules related to angiogenesis (VEGFR), invasion (MMPs), cell adhesion (CDH1, vimentins, claudins), and transcription factors involved in the EMT (Twist, Snail, Zeb)." (PMID 33375038, 2020). "LPD3 cancer samples had over-representation of ETS and PTEN gene alterations, and under-representation of CDH1 and SPOP gene alterations (P < 0.05, χ2 test)." (PMID 32203215, 2020). "TWIST1 belongs to the basic helix-loop-helix (bHLH) transcription family, which is involved in cancer metastasis and flanks the CDH1 gene to repress E-cadherin." (PMID 31963305, 2020). "Western blot assays showed that the decreased CDH1 expression and enhanced mesenchymal (CDH2 and vimentin) and cancer stemness (CD44, ABCG2, OCT4 and MYC) marker expression were abolished after treating MCF-7OE-UBE2O cells with rapamycin." (PMID 31907353, 2020).
cancer (continued). "Expression of cancer stemness markers (PROM1 and LGR5), EMT genes (SNAI1, ZEB1 gene and CDH1) and percentage of ALDH + cells were evaluated to assess the effect of sinensetin in modulating cancer stemness and self-renewal." (PMID 33628166, 2020). "In total, 32 cancer related genes including CCND1, MKI67, HIF1A, CDH1, RRM2, and FOXM1 were subsequently identified through Ingenuity Pathway Analysis." (PMID 32348423, 2020). "Upon induction of EMT, hypermethylation of the CDH1 promoter through DNMTs, which are recruited by EMT-TFs, is constantly observed in a wide variety of cancer cells." (PMID 33343366, 2020). "SNAI1, a transcription factor, is translocated into the nucleus where it inhibits the transcription of epithelial markers such as E-cadherin/CDH1 and promotes metastasis of most cancers." (PMID 30736337, 2019). "qPCR analyses revealed that the mesenchymal markers (i.e. SNAI1, SNAI2, ZEB1, ZEB2, CDH2, vimentin and fibronectin) expression was decreased in cancer EVs-exposed BRCA1-KO fibroblasts, while the expression of CDH1 was increased." (PMID 31200749, 2019). "For example, the top 15 SGA-FIs (ranked according to the FDR p values of overlapping DEG sets) that share DEGs with PIK3CA include PTEN, CDH1, ERBB2, and GATA3, which are known cancer drivers, and their connections agree with existing knowledge." (PMID 31276486, 2019). "The significant reduction in E-cadherin in CAOV3 and SKOV3 cells treated with TGF-β indicates its ability to switch cadherins (CDH1 to CDH2) and induce EMT which is essential for cancer invasion." (PMID 31336560, 2019). "We calculated and plotted the Pearson correlation coefficient r, between the expression of TF genes and the expression of CDH1 or VIM, across 1038 CCLE microarrays for cancer cell lines representing various degrees of E and M states." (PMID 31019211, 2019). "The comparison of tissue samples shows the increasing methylation trend from the control sample group to cancer samples in the RASSF1, CDH1 and PAX1 genes." (PMID 31450846, 2019). "The repressors exert an inactivating effect on CDH1, thus facilitating the EMT and promoting the survival and resistance of cancer cells." (PMID 31212809, 2019). "Our meta-analysis was unable to find any statistical significance between HBV-positive carcinoma tissues and HBV-negative carcinoma tissues for the methylation of the remaining seven genes, including RUNX3, p14, WIF1, CDH1, PRDM2, SOCS1 and MGMT." (PMID 31772678, 2019). "The meta-analysis of GSTP1, RUNX3, SOCS1, CDH1 and SFRP1 genes methylation was performed between HBV-positive carcinoma tissues and HBV-negative carcinoma tissues and between HBV-positive adjacent tissues and HBV-negative adjacent tissues." (PMID 31772678, 2019). "They used four established EMT markers—CDH1 (epithelial marker, E type), CDH2 (mesenchymal marker, M type), VIM (M type), and FN1 (M type)—as seeds to develop a pan-cancer EMT signature on the basis of TCGA pan-cancer RNA-Seq data." (PMID 29426364, 2018). "qRT-PCR performed to validate the microarray results showed that expression of a number of cancer-related genes, including HAS3, CD44, TP63, and SMYD2, was decreased by siRNAs targeting DLEU1, while expression of CDH1 was increased by DLEU1 knockdown." (PMID 30069008, 2018). "The E-cadherin (CDH1) is regulated by PRC2, and its suppression is critical for Epithelial-Mesenchymal Transition (EMT) and cancer metastasis." (PMID 30266084, 2018). "For example, CDH1 and polarity genes (Crumbs3, Lgl2) are known direct target genes repressed by ZEB1 in carcinoma EMT." (PMID 29744893, 2018). "We screened for cancer cells expressing at least one EMT marker, such as ACTA2, EPCAM, CD44, THY1, VIM, FN1, ZEB1 or CDH1." (PMID 29079795, 2017).
cancer (continued). "Moreover, TRIM28 has been demonstrated to regulate EMT gene expression (CDH1 encoding E-CADHERIN and CDH2 encoding N-CADHERIN) through modification of histones of target gene promoters, further implying its role in acquisition of highly aggressive mesenchymal phenotype of cancer cells." (PMID 28851455, 2017). "An unexpected finding was that, in addition to inducing EZH2 expression in cancer cells, MUC1-C was detectable in complexes with EZH2 on the CDH1 and BRCA1 promoters, invoking the notion that MUC1-C associates with EZH2." (PMID 28785086, 2017). "In many cancers, the nucleus β-catenin composes a complex with TCF/LEF1 family to inhibit the transcription of CDH1 and induce EMT by directly stimulating Snail and Slug." (PMID 29383144, 2017). "Correspondingly, the epithelial phenotype with high CDH1 expression, low expression of VIM and low expression of EMT-inducing transcription factors correlates with high expression of cancer stem cell markers CD133 and EPCAM." (PMID 29299154, 2017). "CDH1(E-cadherin) gene involved in invasion and metastasis of cancer cells, LSD1 regulates EMT via demethylation of CDH-1 gene." (PMID 28121627, 2017). "The analysis of the distribution of CDH1 expression levels in normal and cancer tissue samples, following normalization to the GAPDH reference gene, revealed a significantly lower level of CDH1 in tumors compared to normal samples (P = 0.001)." (PMID 27861150, 2017). "Complementary to this notion, previous studies have demonstrated that the metastasis-regulator Snail recruits SUZ12 to the CDH1 promoter and represses E-cadherin expression, thus in turn triggers EMT and cancer metastasis." (PMID 28228691, 2017). "In cancer cell EMT, studies have shown that H3 methyltransferase G9a and H3K9me3 are crucial for silencing of E-cadherin (CDH1) during EMT." (PMID 27566588, 2016). "Previous studies showed that aberrant CDH1 or/and HDAC3 localization is essential for the progression of some human cancers." (PMID 26918727, 2016). "The capacity of cancer cells to migrate and invade other organs using vascular channels is characterized by a variety of genes, such as APC, E-Cadherin (CDH1), H-Cadherin (CDH13) and FAT tumor suppressor cadherin." (PMID 25997695, 2015). "When the MDA-MB-231 cancer cell media was changed from MEM to DMEM for 48 h, expression levels of CDH1 and CD24 were significantly reduced." (PMID 25776572, 2015). "To do so, we compared Pol II pausing signal and expression levels on SNAI1, CDH1 and SNAI2 genes in several cancer cell lines grown in steady-state conditions in the absence of activation." (PMID 25820424, 2015). "High CDH1 (E-cadherin) and low IL1-Beta expression by cancer cells promoted reorganization of hMSCs into a niche-like formation, which was dependent on direct cell-cell contact." (PMID 26204886, 2015). "Another KLF member, KLF8 promotes human BC cell invasion and metastasis by transcriptionally repressing cadherin 1 (CDH1) and transactivating matrix metallopeptidase (MMP9), and high expression of KLF8 predicts a poor prognosis in human cancers." (PMID 25897424, 2015). "However, CDH1 methylation was not shown to be associated with this cancer (p = 0.241)." (PMID 26032781, 2015). "Upon hypoxia, a well-described inducer of cancer cell aggressiveness and EMT, HDAC3 was recruited to epithelial genes such as CDH1 leading to decreased H3K4ac, a subsequent increase in H3K4me2 and H3K27me3, and ultimately gene repression." (PMID 24840099, 2014). "ZEB1 and ZEB2 are key factors regulating CDH1 expression and their connection with EMT and metastasis of cancer cells has been well established." (PMID 24840099, 2014). "The result showed that, CDH1, VEGFA, PTPRF and CLDN7 were up-regulated in six cancer samples, and MMP2 was down-regulated in ten cancer samples, suggested that these genes, especially MMP2, were dysregualted in most UCB samples." (PMID 24622401, 2014).
cancer (continued). "KIT, CDH1, LSM7, C21orf4, DDI2 mRNA expression levels were significantly different between benign and malignant tumors, p(KIT) < 0.0001; p(CDH1) = 0.004; p(LSM7) = 0.03; p(C21orf4) = 0.01; p(DDI2) = 0.0001." (PMID 22958914, 2012). "Among genes downregulated by clofibrate, the major part belonged mainly to functional groups: “cancer” (STIP1, HNRNPA1, VIL1, and CDH1) and “cellular assembly and organization” (CLASP1 and MACF1)." (PMID 22619672, 2012). "Six COPD patients developed cancer after five years from the initial COPD diagnosis at 2006–2007.We also evaluated the frequency of CDKN2A, CDH1 and MGMT promoter methylation in sputum samples of the groups under study." (PMID 22818553, 2012). "Only APC (39%), CCND2 (21%), CDH1 (7%), and RARB (4%) were hypermethylated in >2% of these cancer-free subjects." (PMID 21577262, 2011). "We analysed cdc14A, that regulates centrosome separation and activates the anaphase promoting complex cdh1/APC, Ndc80/Hec1 (Highly Expressed in Cancer;) a component of APC and Aurora Kinase B, a key regulator of chromosome segregation." (PMID 21187932, 2010). "Secondly hypermethylation of CDH1, CDKN2A, and SFRP1, was rare in PCa tissues (<5% of the specimens), although they were hypermethylated in cancer cell line controls." (PMID 15292941, 2004). "We anticipate two potential applications of our findings: first, HDGC-like patients who test negative for CDH1 and CTNNA1 pathogenic variants, who by HDGC definition only have diffuse tumours, should be offered a broader cancer panel." (PMID 40446793, 2025). "In contrast, CDH1, encoding for E cadherin, showed a higher mutation rate in ELF3/HNF4A non-up-regulated cancers (16.7% vs. 6.1% in the up-regulated group), which was not however statistically significant (Student’s t-test p = 0.17)." (PMID 41425714, 2025). "The absence of functional E-cadherin can facilitate the invasive characteristics of cancer cells, contributing to the aggressive nature of DGCs associated with CDH1 mutations." (PMID 40585607, 2025). "In this study, CDH1 expression increased approximately 5-fold in cancer stem cells treated with BA compared to cancer stem cells without BA." (PMID 38963646, 2025). "Indeed, several studies have explored the utility of markers, such as CEA, CDH1, and MGB1 for CTC identification in cancer patient blood." (PMID 40525275, 2025). "Mechanistic insights confirmed the downregulation of several genes associated with the epithelial–mesenchymal transition (EMT) and cancer stemness (e.g., SNAIL1, TWIST1, ZEB1, and ZEB2, E-cadherin (CDH1), Vimentin, CD133, Thy1, CDH2, fibronectin, and alpha-SMA) upon HBx knockdown." (PMID 39459899, 2024). "A significant increase in CDH1 as well as significant decreases in CDH2 and MMP2 gene expression und s-μg indicated an induction of a mesenchymal–epithelial transition (MET) phenotype in the A549 cells, suppressing cancer progression." (PMID 38255998, 2024). "In addition, we predicted the sensitivity of common anti-cancer drugs on prognostic signature, including CCR5, HMOX1, CTSC, CD5, BCL3, CDH1, TYROBP and CD38." (PMID 38767825, 2024). "The analysis of the tumoral markers p27, CD44, Fibulin-3, and NANOG and the expression of genes related to cancer transformation such as NANOG, CDH-1, and Zeb-1 showed that the simulated microgravity environment led to expression patterns in MeT-5A cells similar to those observed in BR95 cells." (PMID 39451527, 2024). "Phosphorylation of its co-activator CDH1 modulates the E3 ligase activity, but little is known about its regulation after phosphorylation and how to effectively harness APC/CCDH1 activity to treat cancer." (PMID 38622115, 2024). "Similarly, several effector molecules, including CALD1, CDH1, FN1, FZD7, RAC1, STAT3, and WNT11, were downregulated in cancer cells treated with DBMSCs." (PMID 39768220, 2024).
cancer (continued). "It mentions that factors like Cadherin 1 and integrin subunits α6 and β4 protect against ferroptosis, while the activation of the Hippo pathway (involving YAP1 and WWTR1/TAZ) promotes ferroptosis in cancer cells." (PMID 38369484, 2024). "Differently from the results on the other three cancer cell lines, the CDH1 expression of HCA7 cells was not significantly affected by mEVs from CRC patients." (PMID 36672299, 2023). "The authors noticed a striking lack of correlation between findings in normal epithelia as compared to cancerous cells with CDH1 being identified as a target in normal epithelia but not cancer." (PMID 36691073, 2023). "CC-3 represented the mesenchymal-like cancer cell subpopulation that expressed mesenchymal genes such as Prrx1, Col6a1, Thy1, and Vim, but not epithelial marker genes such as Epcam and Cdh1." (PMID 37190324, 2023). "Strikingly, the levels of CDH1 mRNA and E-cad protein were not reduced in most of the examined tumors, even in the later stages of cancer compared to respective healthy tissues." (PMID 37189027, 2023). "Consistent with its non-essential role in cell–cell adhesion in non-epithelial tissues/cells, CDH1 levels were lower than those in carcinoma cells." (PMID 37189027, 2023). "CDH1 mRNA and E-cadherin protein are not downregulated in most carcinoma tissues and carcinoma cell lines tested in this study." (PMID 37189027, 2023). "In late-stage cancer, cells seem to become resistant to its anti-mitotic effects and TGFB1 was instead observed to stimulate EMT by upregulating mesenchymal markers (e.g., VIM, CDH2) and downregulating epithelial markers (e.g., CDH1)." (PMID 35565214, 2022). "Thus, by repressing the CDH1 gene and sponging the miR-218-5p, MALAT1 can promote the EMT process and cancer cell metastasis, lead to an increase in Survivin levels and cancer cell resistance to 5FU and oxaliplatin treatment." (PMID 35922756, 2022). "On the other hand, reintroducing CDH1 into non-expressing cells changes the phenotype of poorly differentiated cancers to a well-differentiated, minimal invasive epithelioid type with well-established cell junctions." (PMID 36142368, 2022). "In addition, we analyzed the correlation pair-wise (Pearson’s correlation test), between PEBP1 (RKIP) and SNAI1, VIM, CDH1/2, EPCAM, and LAMA1/B1 genes, across the 22 different types of cancer and normal tissues in the TCGA database." (PMID 36230521, 2022). "First, bioinformatic analysis of publicly available cancer databases (including TIMER 2.0, GEPIA, Oncomine, TCGA, GEO, HPA, and Kaplan-Meier plotter) revealed that highly expressed CDH1 functions as an oncogene in BC and is positively correlated with malignancy progression." (PMID 35784532, 2022). "Unfortunately, no other members of this family decided to perform CDH1 genetic testing for cancer prevention." (PMID 35686104, 2022). "Likewise, low expression levels of CDH1 and high expression levels of VIM and ACTA2 in cancer cells indicate the high metastatic potential of cancers and correlate with the poor prognosis of affected patients." (PMID 35621926, 2022). "The lack of CDH1 will lead to a decrease in the number of adhesion proteins, thereby making cancer more prone to distant metastasis." (PMID 35296343, 2022).